VASP (vasodilator stimulated phosphoprotein)
Diseases named in the same sentence as VASP in open-access papers (continued):
Sharing a sentence is not in itself a finding about the gene and the disease.
breast cancer (continued). "Furthermore, CREB1 can also directly bind to the promoter of VASP, and activate VASP expression, forming a CREB/Lin28/miR-638/VASP interactive network, which plays an important role in promoting cell proliferation and migration in breast cancer." (PMID 31754343, 2019). "However, the current research still cannot fully explain the molecular mechanism of VASP in breast cancer, and has not established an interactive network focus on VASP." (PMID 31754343, 2019). "In addition, Kaplan-Meier plotter database analysis showed a negative correlation between the expression level of VASP and the survival of breast cancer patients (P=0.029)." (PMID 31754343, 2019). "Furthermore, we previously identified that HIF-1α could directly inhibit VASP transcription during the TNF-α-induced metastasis and adhesion of breast cancer MCF-7 cells." (PMID 25051011, 2014). "Next we analyzed a panel of breast cancer cell lines, containing highly-invasive cell lines (MDA-MB-231 and MDA-MB-468) that are metastatic in animal models, as well as hormone receptor-positive cell lines (ZR-75–1, T47D and SKBR3) that are not metastatic in vivo, for VASP phosphorylations." (PMID 26336132, 2015).
melanoma (17 papers, 2010 to 2025). A malignant, usually aggressive tumor composed of atypical, neoplastic melanocytes. "Since the loss of Ena/VASP proteins has been shown before to influence filopodia (e.g. in neurons;) and lamellipodia numbers (e.g. in melanoma cells;), we used the images of phalloidin-stained DCs to quantify filopodia and lamellipodia in DCs before and after maturation." (PMID 36274843, 2022). "We identified 2 compounds reducing melanoma cell viability and mobility and found that they differently affect the phosphorylation pattern of the vasodilator-stimulated phosphoprotein (VASP), a cytoskeletal protein linked to apoptosis, proliferation and migration." (PMID 29435180, 2018). "To test the hypothesis of whether Ena/VASP proteins are essential for filopodia formation in CP-deficient cells, we first disrupted the single gene (CapZb) encoding the ß-subunit of CP in B16-F1 mouse melanoma cells using CRISPR/Cas9 technology." (PMID 36980231, 2023). "Consistently, VASP accumulation at lamellipodia tips was shown to positively correlate with protrusion rates in B16-F1 mouse melanoma cells and fish keratocytes." (PMID 32391788, 2020). "The role of Wnt5A mediated signaling in cell motility and other intermediary proteins (e.g. Ena/VASP, Arp2/3) in filopodia formation has been investigated in human and mouse melanoma cells." (PMID 20454608, 2010). "Much like the results presented here, Ena-VASP-hMena triple knockout cells (mouse fibroblasts and melanoma cell lines) had aberrant lamellipodial morphology which was concordant with a loss of lamellipodial F-actin network organization and decreased F-actin content." (PMID 36238292, 2022). "Interestingly, evidence for VASP-dependent changes in the cortical actin network has recently been shown in B16 melanoma cells." (PMID 34042588, 2021). "From these results, we speculated that Myo10 transports VASP to the tips of filopodia protruding from pseudopods in melanoma cells." (PMID 29993000, 2018). "Melanoma mice deficient of VASP had stunted growth, decreased tumor size, impaired nutrition, and less vascularization compared to control mice revealing the role of VASP in non-tumor cells in the tumor environment." (PMID 33171868, 2020). "To evaluate the function of Ena/VASP proteins in cell migration in a comparably fast mesenchymal cell type, we sequentially inactivated the three Ena/VASP paralogues Evl, VASP and Mena using CRISPR/Cas9 technology in B16-F1 mouse melanoma cells." (PMID 32391788, 2020). "In this study, we sought to explore the role of VASP in CuB-induced disruption of actin cytoskeleton in human A375 and mouse B16F10 melanoma cell lines." (PMID 24691407, 2014). "Furthermore, results of GEPIA analysis showed that ACTB, SLC1A5, VASP, BRBB3, GAS7, ARTN2, and SOX5 were significantly increased in melanoma tissues (p < 0.05)." (PMID 38561355, 2024). "Co-treatment with resveratrol and 5-Fluorouracil (5-FU) reduced tumor growth in the B16 murine melanoma model by the alteration of the expression levels of AMPK, VASP, and VEGF and suppressed angiogenesis by the decrease in the number of microvascular vessels compared with the control group." (PMID 36829966, 2023). "The combination treatment with resveratrol and 5-FU on B16 murine melanoma cells suppressed metastasis by inhibiting cell migration and tumor growth and angiogenesis by downregulating the expression levels of COX-2, VEGF, and VASP." (PMID 36829966, 2023). "In this study, we showed that VASP was phosphorylated at Ser157 by CuB treatment in a time- and dose-dependent manner in both A375 and B16F10 melanoma cells." (PMID 24691407, 2014).
gastric cancer (11 papers, 2018 to 2025). A primary or metastatic malignant neoplasm involving the stomach. "Based on these results, we sought to characterize the functional significance of the regulation of VASP expression by miR-4455, and found that inhibition of VASP expression resulted in significant loss in the number of invasive gastric cancer cells." (PMID 30002604, 2018). "For example, icariin, a purified extract from the Herba epimedium (a traditional Chinese medicine), adversely impacts the invasion and migration of gastric cancer cells through the Rac1-dependent vasodilator-stimulated phosphoprotein (VASP) pathway." (PMID 41188920, 2025). "Reports suggest that BA inhibited gastric cancer cell migration and invasion by impairing epithelial‐mesenchymal transition signaling and targeting the NF-κB/VASP signaling pathway." (PMID 39164686, 2024). "In gastric cancer cells, the expression of VASP can be inhibited by miR-4455, thereby reducing VASP-mediated properties such as proliferation, migration, stemness and invasion." (PMID 36355541, 2022). "VASP is inhibited by miR-4455 functions as a tumor suppressor in gastric cancer cells which decreased VASP-mediated proliferation, migration, and invasion." (PMID 33171868, 2020). "MA also significantly inhibited the cell migration and adhesion of BGC-823 gastric cancer cells by changing the subcellular distribution of the cytoskeleton protein vasodilator-stimulated phosphoprotein (VASP) and formation of actin stress fibers." (PMID 33167519, 2020). "Matrine can regulate the structure and subcellular distribution of vasodilator-stimulated phosphoprotein (VASP) in gastric cancer BGC823 cells, thereby inhibiting the adhesion and migration of cancer cells." (PMID 32477114, 2020). "Studies have shown that VASP participates in the development of tumors such as gastric cancer and cervical cancer 11-15." (PMID 31754343, 2019). "To test this, we used multiple transfection assays to confirm that VASP expression is regulated by miR-4455; Overexpression of miR-4455 in gastric cancer cells resulted in a significant downregulation of VASP expression at both the protein and mRNA levels." (PMID 30002604, 2018). "The results indicate that miR-4455 is a novel regulatory miRNA that targets VASP in gastric cancer cells, and suggest that the miR-4455-VASP-PI3K/AKT axis offers potential as a novel therapeutic target for the inhibition of gastric cancer progression and metastasis." (PMID 30002604, 2018). "Existing research has suggested that VASP plays an important role in regulating the proliferation, invasion and migration of gastric cancer cells, but the mechanism of these effects remains unclear." (PMID 30002604, 2018). "In conclusion, our data demonstrate that miR-4455 suppresses tumorigenesis in GC cells in vitro, by directly targeting VASP in GC cells, finally leading to the inhibition of VASP mediated proliferation, migration and invasion of gastric cancer cells." (PMID 30002604, 2018). "Another study demonstrated that MT significantly down-regulated the expression and phosphorylation of vasodilator-stimulated phosphoprotein (VASP), which is up-regulated in gastric cancer cells (BCG823), thereby suppressing tumor cell migration and adhesion." (PMID 33041782, 2020). "Our results suggest that miR-4455 functions as a tumor suppressor in gastric cancer, by targeting VASP leading to activation of the PI3K/AKT signaling pathway and the inhibition of VASP mediated proliferation, migration and invasion of gastric cancer cells." (PMID 30002604, 2018).
colon cancer (8 papers, 2015 to 2024). "Studies using colon cancer cells (HCT116) revealed that genistein-mediated antimetastatic effects via inhibition of COX-2 and MMP-9, Ang-1, vasodilator-stimulated phosphoprotein (VASP) and VEGF." (PMID 31866857, 2019). "Phosphorylations of VASP at S239 and T278 are mainly mediated by PKA, PKG and AMPK; and suppress motility in cancer cells and colon cancer." (PMID 26336132, 2015). "Treatment of human colon tumor cells with Pf-2545920 activated both PKG and PKA, which occurred in a time and concentration-dependent manner, as shown by the phosphorylation of the PKG and PKA substrate VASP, as well as by the PKA substrate CREB." (PMID 26713600, 2016).
hepatocellular carcinoma (8 papers, 2020 to 2025). A malignant tumor that arises from hepatocytes. "In hepatocellular carcinoma, vasodilator-stimulated phosphoprotein (VASP) acts as a tumor premotor and its overexpression at the transcriptional level is mediated by direct binding of HIF-1α to HREs in the VASP promoter region." (PMID 32014012, 2020). "Experimental evidence from research into a hepatocellular carcinoma cell line has shown that HIF-1α mediates vasodilator-stimulated phosphoprotein (VASP) overexpression at the transcriptional level by directly binding to the promoter of the VASP gene." (PMID 34884541, 2021). "In hepatocellular carcinoma (HCC) hypoxia upregulated VASP by binding to hypoxia response elements (HRE) in the VASP promoter region." (PMID 33171868, 2020). "In hepatocellular carcinoma (HCC), VASP expression has been shown to promote metastasis." (PMID 39792809, 2025).
ischemia (8 papers, 2011 to 2023). A hypoperfusion of the BLOOD through an organ or tissue caused by a PATHOLOGIC CONSTRICTION or obstruction of its BLOOD VESSELS, or an absence of BLOOD CIRCULATION. "Surprisingly, however, vascular repair and blood flow recovery were increased after ischemia in VASP-deficient mice." (PMID 37443774, 2023). "VASP, the actin‐associated protein involved in a range of processes, has been revealed as a key regulator of macrophage M2 polarization after ischemia and in HFD‐induced hepatic inflammation." (PMID 34084287, 2021). "VASP-deficiency increased leukocyte infiltration, polarization, and vascular repair after ischemia." (PMID 37443774, 2023). "Given the clinical importance of hepatic IR injury we pursued the role of VASP during hepatic ischemia followed by reperfusion." (PMID 22216296, 2011). "The preconditioning-induced VASP phosphorylation inactivates αIIbβ3 integrin receptor on platelets, which results in the reduced formation of organ compromising PNCs, demonstrating that VASP phosphorylation in platelets is a protective mechanism against the deleterious effects of ischemia." (PMID 37443774, 2023). "First, data on cutoff values for VASP index in a setting of TAT regimen are limited, and it may well be that cutoff values that best determine patients risk for ischemia or bleeding may differ in this cohort compared with values obtained in patients with antiplatelet treatment alone." (PMID 33917717, 2021). "Using several ex vivo and in vivo approaches we confirmed cybernetic parameters, such as controller, sensor, and effector (VASP phosphorylation, P2Y12, ADORAs and GPIIb/IIIa activity), as well as set points (ADP, adenosine) and interfering control and disturbance variables (ischemia)." (PMID 36230973, 2022). "On the contrary, another member of the phosphoproteins, the vasodilator-stimulated phosphoprotein (VASP), produced from mononuclear cells, can form complex with CCR2 and β-arrestin 2, leading to reduced infiltration of leukocytes into the injury site after ischemia." (PMID 32878297, 2020).
diabetes (7 papers, 2018 to 2025). "VASP phosphorylation at S239, associated with vascular permeability in diabetes, decreased dramatically (log2FC = −10.12, adjusted p = 1.58 × 10−6)." (PMID 40940763, 2025). "Increased concentrations of VASP have been identified in obesity, and it was also shown that elevated levels are associated with diabetes mellitus, metabolic syndrome, obesity and coronary artery diseases." (PMID 36294546, 2022). "Diabetes causes a decrease in the phosphorylation and intracellular redistribution of vasodilator-stimulated phosphoprotein (VASP), an actin motor protein needed for cell migration, which in turn causes the homing of CD34+ cells from the peripheral blood of diabetic human patients to be defective." (PMID 31575089, 2019). "Reflecting the lower levels of active metabolites, inhibition of the VASP-PRI and platelet aggregation in diabetes was attenuated in prasugrel treatment." (PMID 29568240, 2018). "In univariate analysis, bSS > 22, rSS > 8, PCI, age, diabetes mellitus, cardiovascular disease heredity, chronic kidney disease, and PRI VASP (platelet reactivity index vasodilator stimulated phosphoprotein) post-TAVR were significant predictors for myocardial infarction occurrence." (PMID 32708771, 2020). "Although diabetes did not affect VASP-PRI in clopidogrel-treated patients, sleep-disordered breathing assessed by the oxygen desaturation index showed a positive correlation." (PMID 29568240, 2018). "To determine the importance of diabetes on drug metabolism and inhibition of platelet aggregation, we compared active metabolite concentrations, the VASP-PRI, and inhibition of platelet aggregation induced by 20 μM ADP in patients with diabetes and those without diabetes." (PMID 29568240, 2018).
glioma (7 papers, 2021 to 2024). A benign or malignant brain and spinal cord tumor that arises from glial cells (astrocytes, oligodendrocytes, ependymal cells). "Next, A172 and U251 cells were administrated with sh-NC, sh-circRFX3#1, sh-circRFX3#1 + vector or sh-circRFX3#1 + VASP to explore the association between circRFX3 and VASP in glioma cell progression." (PMID 34727925, 2021). "In this paper, the expression profiles of circRFX3, miR-1179, miR-1229 and VASP in glioma tissues and cells were determined." (PMID 34727925, 2021). "Additionally, vasodilator stimulated phosphoprotein (VASP) participated in regulating glioma carcinogenesis by serving as the sponge of miR-605-3p." (PMID 34727925, 2021). "Additionally, VASP elevation overturned the influences of circRFX3 silencing on glioma cell proliferation, motility and apoptosis, suggesting that circRFX3 stimulated glioma cell progression via elevating VASP expression." (PMID 34727925, 2021). "Additionally, VASP was demonstrated to be the target gene of miR-1179 and miR-1229, and VASP overexpression abolished the effect of circRFX3 knockdown on glioma cell progression." (PMID 34727925, 2021). "All these data demonstrated that circRFX3 knockdown could repress the malignant phenotypes of glioma cells by regulating VASP." (PMID 34727925, 2021). "Even so, there is no report on the interaction between miR-1179/miR-1229 and VASP in glioma." (PMID 34727925, 2021).
pancreatic cancer (6 papers, 2018 to 2025). "Then, the correlation of IGF2BP3, EMP1, and VASP expression was analyzed in the TCGA-PAAD data cells, and results revealed that the expression of EMP1 or IGF2BP3 was positively correlated with VASP in pancreatic cancer." (PMID 41285728, 2025). "In a previous study, FAT2 was found to share the signaling pathway like Ena/VASP, which affects progression of gastric and pancreatic carcinoma." (PMID 36812126, 2023). "VASP was involved in the regulatory network of miRNA–mRNA to contribute to the development of gemcitabine resistance in human pancreatic cancer cells." (PMID 33385064, 2021). "Together, our data support VASP as a treatment target for liver metastasis of colorectal and pancreatic cancers." (PMID 29872721, 2018). "Finally, VASP was identified by mass spectrometry as a protein that specifically binds to EMP1 in pancreatic cancer cells." (PMID 41285728, 2025). "The development of strategies to modulate the activation of the TGF-β/Smads signaling pathway by targeting the IGF2BP3/EMP1/VASP axis may hold promise to improve the current plight of pancreatic cancer." (PMID 41285728, 2025). "Immunofluorescence staining confirmed the colocalization of VASP and SMAD7 in pancreatic cancer cells." (PMID 41285728, 2025). "In conclusion, we found that the EMP1-promoted binding of VASP and SMAD7 in pancreatic cancer promotes the activation of the TGF-β/Smads signaling pathway characterized by enhanced phosphorylation of SMAD2/3." (PMID 41285728, 2025). "Interesting, we found six genes E2F7, CDC6, MMP14, PLK1, VASP and PKM2 were significantly correlated with the prognosis of patients with pancreatic cancer in TCGA, GSE71729, GSE78229 and GSE79668 datasets." (PMID 32950968, 2020). "In a Matrigel-based 3-dimensional (3D) culture model, short hairpin RNA (shRNA)–mediated VASP knockdown in colorectal cancer cells (KM12L4, HCT116, and HT29) and pancreatic cancer cells (L3.6 and MIA PaCa-1) suppresses the growth of 3D cancer spheroids." (PMID 29872721, 2018). "The interactions between EMP1 and VASP were confirmed using co-immunoprecipitation (Co-IP) assays, and immunofluorescence staining confirmed the colocalization of EMP1 and VASP in pancreatic cancer cells." (PMID 41285728, 2025). "Besides, Co-IP analysis illustrated that in pancreatic cancer cells, SMAD7 could bind to the VASP protein, and after knockdown of EMP1 protein in pancreatic cancer cells, the ability of VASP protein binding to SMAD7 was inhibited, and the reverse result was obtained by overexpression of EMP1." (PMID 41285728, 2025).
prostate carcinoma (5 papers, 2015 to 2024). A carcinoma that arises from epithelial cells of the prostate gland. "The effects of LPA on actin-related proteins such as vasodilator-stimulated phosphoprotein (VASP) were also observed to play a role in cell motility and metastases in prostate cancer cells by stimulating the formation of lamellipodia." (PMID 34440828, 2021). "For example, S157 phosphorylation of VASP has been suggested as a marker for prostate cancer cell motility and potential of metastatic progression." (PMID 26336132, 2015). "This indicates that VASP may play a role in the migration and invasion processes of prostate carcinoma cells, contributing to the disease progression." (PMID 39641316, 2024). "Activation of β2-AR signaling induces phosphorylation of PKA substrates CREB, vasodilator-stimulated phosphoprotein (VASP), Bcl-2 antagonist of cell death (BAD) and increases expression of myeloid cell leukemia 1 (MCL-1), leading to inhibition of apoptosis in prostate cancer." (PMID 33419318, 2020).